MSGN1 (mesogenin 1)
Description:
Involved in specifying the paraxial, but not dorsal, mesoderm. May regulate the expression of T-box transcription factors required for mesoderm formation and differentiation (By similarity).
Synonyms: pMsgn1; pMesogenin1; MSOG
Tractability: No criterion of Open Targets' tractability assessment is met for any kind of drug.
Gene: Protein-coding gene on chromosome 2 (17,816,460 to 17,817,798, forward strand). Ensembl gene ENSG00000151379.
Subcellular location: Nucleus
Subcellular location (Human Protein Atlas): Acrosome; Equatorial segment; Mid piece
Pathways (Reactome):
Developmental Biology: Formation of paraxial mesoderm; Somitogenesis
Gene Ontology:
Molecular function: protein binding; sequence-specific double-stranded DNA binding; DNA-binding transcription factor activity, RNA polymerase II-specific; RNA polymerase II cis-regulatory region sequence-specific DNA binding; chromatin binding; DNA-binding transcription activator activity, RNA polymerase II-specific; DNA-binding transcription factor activity; protein dimerization activity
Biological process: mesoderm formation; regulation of transcription by RNA polymerase II; positive regulation of transcription by RNA polymerase II
Cellular component: chromatin; nucleus
Genetic constraint (gnomAD): Loss-of-function variants: 3 observed, 10.96 expected, observed/expected ratio (o/e) 0.27, 90% interval 0.12 to 0.71. The upper end of that interval is the gene's LOEUF score, 0.71, which puts it in group 2 of 6, group 1 being the genes least tolerant of losing a copy. Missense variants: 244 observed, 257.05 expected, observed/expected ratio (o/e) 0.95, 90% interval 0.85 to 1.05. Synonymous variants: 110 observed, 109.23 expected, observed/expected ratio (o/e) 1.01, 90% interval 0.86 to 1.18.
Homologues: Orthologues: chimpanzee MSGN1 (99% identical), macaque MSGN1 (97% identical), pig MSGN1 (90% identical), rabbit MSGN1 (90% identical), dog MSGN1 (80% identical), mouse Msgn1 (77% identical), guinea pig MSGN1 (74% identical), rat Msgn1 (63% identical), tropical clawed frog msgn1 (42% identical), zebrafish msgn1 (33% identical), Drosophila melanogaster sage (22% identical). Paralogues in human: MESP2 (27% identical), MESP1 (26% identical).
Diseases named in the same sentence as MSGN1 in open-access papers:
MSGN1 is named in the same sentence as 1 disease in open-access papers, as found by Europe PMC text mining. Sharing a sentence is not in itself a finding about the gene and the disease. The quoted sentences say what the papers report.
tumor (1 paper, 2021). "MSGN1, ISM2, HAS1, RETN, MMP19, C1QTNF1, and F13A1 were all involved in the regulation of tumors, but their involvement in the regulation of tumor immunity is not clear." (PMID 34177903, 2021).